AAMDC (adipogenesis associated Mth938 domain containing)
Description:
May play a role in preadipocyte differentiation and adipogenesis.
Synonyms: C11orf67; PTD015; FLJ21035; CK067
Tractability: PROTAC: ubiquitination databases record sites on it; its protein half-life has been measured.
Gene: Protein-coding gene on chromosome 11 (77,821,100 to 77,918,432, forward strand). Ensembl gene ENSG00000087884.
Subcellular location: Cytoplasm
Subcellular location (Human Protein Atlas): Nucleoplasm; Cytosol
Gene Ontology:
Molecular function: protein binding
Biological process: positive regulation of fat cell differentiation
Cellular component: cytoplasm
Genetic constraint (gnomAD): Loss-of-function variants: 14 observed, 13.84 expected, observed/expected ratio (o/e) 1.01, 90% interval 0.67 to 1.57. The upper end of that interval is the gene's LOEUF score, 1.57, which puts it in group 6 of 6, group 1 being the genes least tolerant of losing a copy. Missense variants: 129 observed, 134.43 expected, observed/expected ratio (o/e) 0.96, 90% interval 0.83 to 1.11. Synonymous variants: 44 observed, 47.59 expected, observed/expected ratio (o/e) 0.92, 90% interval 0.73 to 1.19.
Homologues: Orthologues: chimpanzee AAMDC (100% identical), rabbit AAMDC (93% identical), mouse Aamdc (92% identical), pig AAMDC (90% identical), guinea pig AAMDC (89% identical), rat Aamdc (89% identical), dog AAMDC (88% identical), zebrafish aamdc (76% identical), tropical clawed frog aamdc (74% identical), macaque AAMDC (68% identical).
Diseases named in the same sentence as AAMDC in open-access papers:
AAMDC is named in the same sentence as 4 diseases in open-access papers, as found by Europe PMC text mining. Sharing a sentence is not in itself a finding about the gene and the disease. The quoted sentences say what the papers report.
breast carcinoma (1 paper, 2021). "Adipogenesis associated Mth938 domain containing (AAMDC) represents an uncharacterized oncogene amplified in aggressive estrogen receptor-positive breast cancers." (PMID 33772001, 2021). "Adipogenesis associated Mth938 Domain Containing gene (AAMDC) is frequently amplified in the IntClus2 subgroup of ER + breast cancer." (PMID 33772001, 2021).
toxoplasmosis (1 paper, 2024). A parasitic disease contracted by the ingestion or fetal transmission of toxoplasma gondii. "The pivotal genes AAMDC, GPR158, RAD9A, STOML1and STRA13 identified in this study have the potential to serve as molecular therapeutic or immunotherapeutic targets for toxoplasmosis; however, their specific function mechanisms require further verification." (PMID 39935538, 2024).
cancer (2 papers, 2021 to 2024). A tumor composed of atypical neoplastic, often pleomorphic cells that invade other tissues. "Both RabGAP1L and AAMDC were co-expressed on the plasma-membrane, in the cytoplasm, and/or in the nucleus of luminal cancer cells, as assessed by IF." (PMID 33772001, 2021). "AAMDC+ cancers exhibited the highest expression in the cytoplasm, with relatively frequent but a lower level of nuclear and membrane-associated staining." (PMID 33772001, 2021). "In certain types of cancers, AAMDC proteins may have either promotional or inhibitory effects." (PMID 39935538, 2024). "In this context, the AAMDC-RabGAP1L complex could play a role in the regulation of vesicle trafficking, potentially altering the recycling of small G proteins and thus remodeling the cancer signaling network." (PMID 33772001, 2021).
tumor (2 papers, 2021 to 2025). "In summary, our results indicate that AAMDC constitutively activates PI3K-AKT-mTORC1 signaling to support tumor growth, notably under conditions of metabolic stress such as growth factor and E2 deprivation." (PMID 33772001, 2021). "In vivo, AAMDC overexpression was sufficient to activate the growth of E2-dependent tumor cells under metabolic stress conditions (low levels of growth factor and E2 deprivation)." (PMID 33772001, 2021). "Furthermore, the AAMDC KDs reduced cell migration, a finding consistent with altered F-actin organization and significantly decreased xenograft tumor burden in mice." (PMID 33772001, 2021). "Ectopic AAMDC expression is sufficient to activate AKT signaling, resulting in estrogen-independent tumor growth." (PMID 33772001, 2021). "The lowest expression of AAMDC was detected in ER− tumor cell lines and in non-transformed primary human mammary epithelial cells (HuMEC) and MCF-12A cells." (PMID 33772001, 2021). "Our findings suggest a role of AAMDC as a molecular metabolic switch whereby upregulation of AAMDC through copy number amplification could help sustain ligand-independent activation of PI3K-AKT, and thus supporting tumor survival under metabolic stress conditions, such as E2 deprivation." (PMID 33772001, 2021).